TNF (tumor necrosis factor)
Diseases named in the same sentence as TNF in open-access papers (continued):
Sharing a sentence is not in itself a finding about the gene and the disease.
preeclampsia (continued). "However, levels of TNF alpha, IL-6, IL-8 and IL-10 in premature infants were found to be unaffected by the mother’s preeclampsia condition." (PMID 32063926, 2020). "However, other sources must contribute to the increase of circulating levels of TNF-α during preeclampsia, as peripheral blood leukocytes." (PMID 30618843, 2018). "Increase in the maternal circulating levels of proinflammatory cytokines tumor necrosis factor alpha (TNF α), interleukin (IL)-6, and also the anti-inflammatory cytokine IL-10 in the third trimester of pregnancy in women affected by preeclampsia have been demonstrated in a meta-analysis." (PMID 30483272, 2018). "Nonetheless, serum TNF-α concentrations have been positively and significantly correlated with diastolic BP and uric acid levels, and it has hence been proposed as a potential marker of the severity of preeclampsia." (PMID 30079067, 2018). "In addition, the lower expression of the natural cytotoxicity receptor, NKp46, on NK cells in women with preeclampsia has been suggested to increase the production of the pro-inflammatory cytokine, TNF-α, which further drives a shift in NK cells." (PMID 30079067, 2018). "Possible mechanisms by which dominant Th1 immune responses induce the clinical aspects of preeclampsia are not completely known, but many of the respective Th1 cytokines (TNF-α, IL-2, IL-12, IL-18, and IFN-γ) have been reported to induce apoptosis of trophoblasts." (PMID 30079067, 2018). "Moreover, observed effects of TNF-α on autophagy markers in human first-trimester placenta were compared to term placenta and early-onset preeclampsia cases." (PMID 28097431, 2017). "Maternal plasma concentration of TNF-α is elevated in preeclampsia." (PMID 28738067, 2017). "The aim of the present study was to examine plasma AT1-AA titer in severe preeclampsia and determine whether change in AT1-AA level was associated with TNF-α and VEGF." (PMID 27381670, 2016). "Moreover, a high level of TNF-α has been found in plasma from patients with preeclampsia; however, the role of TNF-α in the failure of spiral artery remodeling and the mechanisms involved in this phenomenon still are not fully elucidated." (PMID 25302305, 2014). "Targeting of the inflammatory cascade set off by increased TNF-α levels could be an important target in the development of preeclampsia therapeutics." (PMID 25249978, 2014). "Besides, the cytokines involved in preeclampsia TNFα and IL-1β upregulate GM-CSF mRNA in cultured first-trimester human decidual cells." (PMID 24987708, 2014). "While several studies found a significant correlation between a specific genotype at position -308 TNF-α and susceptibility to preeclampsia, a meta-analysis of 16 studies found none." (PMID 24719701, 2014). "Several in Vitro and animal studies also support and clarify the role of TNF-α in preeclampsia." (PMID 24719701, 2014). "The placenta is home to a variety of hematopoietic cells, including T cells, natural killer (NK) cells, and macrophages, and all have roles in production of cytokines including TNF-α and pro-inflammatory interleukins that exacerbate the immune response in preeclampsia." (PMID 25249978, 2014). "Plasma levels of TNF-α are elevated in women with preeclampsia." (PMID 23580870, 2013). "However, consistent with these findings, CYP2J2 is up-regulated in preeclampsia and is induced in a trophoblast cell line with TNFα." (PMID 24058654, 2013). "Some studies report higher TNF-α levels in women with established preeclampsia." (PMID 22523688, 2012). "Thus, maintaining high TNF-α levels in systemic circulation may be responsible for the stimulation or disruption of vascular endothelium in the distant time after the removal of the causing factor of preeclampsia which could be expressed by increased production in the systemic circulation of IL -6." (PMID 21253506, 2010).
preeclampsia (continued). "Ischemic placenta leads to endothelial cell activation/dysfunction and enhances TNF-alpha synthesis which leads to induced structural and functional alterations in endothelial cells leading to preeclampsia via transcriptional regulation of the endothelin-1 gene by TNF-alpha." (PMID 21253506, 2010). "Many authors suggest that elevated circulating TNF-alpha levels may be involved in the pathogenesis of preeclampsia." (PMID 21253506, 2010). "On the contrary, the elevated maternal concentrations of TNF-alpha may be a part of the pathogenesis of preeclampsia." (PMID 21253506, 2010). "We have also examined whether the temporal changes in plasma TNF-alpha and IL-6 levels from the antepartum to the postpartum period correlate with the regression of preeclampsia." (PMID 21253506, 2010). "Furthermore, there is no information about maternal blood concentrations of IL-6 and TNF-alpha in women with preeclampsia long time after delivery." (PMID 21253506, 2010). "Thus, increased TNF expression in CD56+ cells is already observed at the stage of gestational hypertension and persists with the development of preeclampsia, reflecting the activation of inflammatory and cytokine-mediated mechanisms in the pathogenesis of these conditions." (PMID 41463130, 2025). "Yet, other factors that upregulate SREBP2 include tumor necrosis factor-α, interleukin-1β, and nuclear factor kappa B. These factors are upregulated in preeclampsia and can be inhibited by statins, and thus, their suppression might also explain why statins would lower chemerin." (PMID 38361240, 2024). "We previously found that VDR and miR-126 expression was reduced in maternal systemic endothelial cells in preeclampsia, and that, vitamin D could inhibit TNF-α-induced vascular cell adhesion molecule (VCAM) expression/production in endothelial cells by promoting miR-126 expression." (PMID 34045549, 2021). "Moreover, UC-MSC improved angiotensin receptor agonistic autoantibody (AT1-AA)-induced pregnancy hypertension and reduced the serum levels of TNF-α, providing further evidence that UC-MSCs may be a possible therapy for preeclampsia." (PMID 33050021, 2020). "Moreover, elevated levels of both TNFα and IL-6 were identified in women with preeclampsia." (PMID 31186952, 2019). "Nonetheless a correlation between preeclampsia and elevated circulating maternal TNF and umbilical levels of the soluble form of TNF receptor 1 has repeatedly been found, suggesting that treatment with TNFi, theoretically, could protect against preeclampsia." (PMID 29751529, 2018). "In this regard, we suggest that an increase in endothelial production of TNFα levels in response to low oxygen tension-induced release of placental exosomes early in gestation might be a common characteristic of pathological pregnancies (e. g. preeclampsia)." (PMID 28350871, 2017). "Interestingly, the AT1-AA has been shown to induce the production of TNF-α in pregnant mice, suggesting that it might be one of the upstream regulators of TNF-α production in preeclampsia patients." (PMID 25249978, 2014). "High INF-γ and TNF-α levels inhibit trophoblast migration and are directly toxic to trophoblasts, so they may contribute to the initial improper remodeling that leads to preeclampsia." (PMID 25249978, 2014). "The source of excess TNF-alpha in preeclampsia remains unclear." (PMID 21253506, 2010). "In vitro BeWo cell culture and treatment with TNF-α and IGF-1 supports studies on different inflammatory conditions including preeclampsia." (PMID 41155321, 2025). "It was reported that decidual DCN expression was increased in preeclampsia (PE) patients, and peripheral levels of both DCN and TNF-α were elevated in PE patients before the appearance of clinical signs, serving as predictive biomarkers for PE." (PMID 39508749, 2025).
preeclampsia (continued). "The average CD56+TNF+ lymphocyte count in the control group (15.95; IQR 1.84) was significantly higher than in women with gestational hypertension (1.42; IQR 1.06) and preeclampsia (2.19; IQR 2.31)." (PMID 41463130, 2025). "Studies have consistently reported elevated levels of various cytokines in preeclampsia, including PGE2, TNF-α, IL-1, IL-6, and CRP." (PMID 38672972, 2024). "Moreover, in a study on the angiogenic potential of ADSCs in patients with preeclampsia (PE), MSCs showed an increased expression of senescence-associated secretory phenotype (SASP) components, including interleukins-6 and -8 and MCP-1, following exposure to TNF-alpha in vitro." (PMID 39125960, 2024). "Inflammatory markers such as tumor necrosis factor-α (TNF-α) and Interleukin-6 (IL-6) are elevated in GDM and preeclampsia." (PMID 37764061, 2023). "TNF-α and CRP levels were also significantly higher in preeclampsia than in the control group and normal pregnancy." (PMID 37700972, 2023). "They concluded that their observations are consistent with a major role for TNF-α in mediating endothelial disturbances, and suggest a key role for TNF-α in the development of preeclampsia." (PMID 36979841, 2023). "In a study using a rat model of preeclampsia, reduced placental blood flow (RUPP-model) led to oxidative stress and increased proinflammatory cytokines like IL-6, IL-17, and TNFα." (PMID 37893042, 2023). "However, while TNF-α production subsides in normal pregnancy by the third trimester, its production during late gestational stages has been observed under pathological conditions such as preeclampsia as well as in placental infections with human cytomegalovirus (HCMV)." (PMID 35100011, 2022). "When we analyzed other inflammatory markers such as tumor necrosis factor alpha (TNF-α), we observed significantly increased levels of this marker in the group of women with preeclampsia (p < 0.03) compared to women with normal pregnancies." (PMID 36034841, 2022). "Women with preeclampsia produce excessive angiotensin II type 1-receptor autoantibody (AT1-AA), soluble fms-like tyrosine kinase-1 (sFlt-1), ox-LDL, and tumor necrosis factor-α (TNF-α), leading to high concentrations of them in the circulation." (PMID 36552639, 2022). "It was found that Th17 in normal pregnant rats induced activation of NK cells, increased plasma TNF-α levels, and decreased placental VEGF, ultimately leading to preeclampsia-related symptoms." (PMID 36700203, 2022). "Proinflammatory cytokines (TNF-α, IFN-γ, IL-2, IL-8, and IL-6) are significantly elevated in preeclampsia." (PMID 33680514, 2021). "TNFα and INFγ are not causally associated with the parturition process but are elevated with inflammatory conditions associated with pregnancy such as chorioamnionitis, exposure to environmental pollutants, preterm rupture of membranes, preeclampsia, gestational diabetes, and preterm birth." (PMID 34959801, 2021). "Inflammatory markers such as cytokines (IL-1b, IL-6, TNF-α, INF-γ) are involved in the pathogenesis of preeclampsia." (PMID 33809556, 2021). "TNF-α combined with VEGF were similarly related to vascular placental dysfunction, leading to plasma overflow and preeclampsia." (PMID 32316163, 2020). "In a lipopolysaccharide (LPS)-induced preeclampsia rat model, UC-MSC transplantation improved preeclampsia symptoms and reduced the levels of inflammatory cytokines such as TNF-α and IL-6." (PMID 33050021, 2020). "Lymphocyte T cells can significantly increase the production of inflammatory cytokines such as tumor necrosis factor alpha (TNFα) and interleukin-6 (IL6), as shown in preeclampsia." (PMID 32116801, 2020). "Adipose tissue staining revealed higher expression of TNF-alpha and MCP-1 in preeclampsia compared to normotensive pregnancy (p < 0.001 and p = 0.024, respectively), indicating increased fat inflammation." (PMID 31521202, 2019).
preeclampsia (continued). "In addition, since development of preeclampsia was reported to be caused by defective trophoblastic invasion, probably through increased pro-inflammatory cytokine TNF-α and decreased IL-10, and VD was also reported to act as an immune modulator by downregulating TNF-α and upregulating IL-10." (PMID 29225576, 2017). "TNF-α, IL-1β, and IL-6 are essential in early pregnancy, but, with the evolution of gestation, high TNF-α levels can promote preeclampsia and gestational diabetes mellitus, while low IL-10 levels are associated with preterm birth." (PMID 27294162, 2016). "Real-time PCR analysis showed increased expression of inflammatory markers TNF-α, TLR-9 and ICAM-1 respectively in endothelial cells treated with preeclampsia plasma." (PMID 27604418, 2016). "The inflammatory markers, IL6, TNF α and CRP were significantly higher in the group with severe preeclampsia." (PMID 26113950, 2015). "Cytokines, such as tumor necrosis factor α (TNF-α), interleukin (IL)-6 and monocyte chemoattractant protein-1 (MCP-1), were increased systemically and locally in the placenta of preeclampsia-bearing women." (PMID 25853857, 2015). "This study reports a statistically significant difference in the levels of the pro inflammatory cytokines, IL 6 and TNF α and in CRP levels in the women with severe preeclampsia, compared with women with normotensive pregnancy." (PMID 26113950, 2015). "This study reports increased levels of the inflammatory cytokines, IL6, TNF α and the marker of inflammation, CRP in severe preeclampsia." (PMID 26113950, 2015). "In the past decades, serum levels of TNF-α had elevated and increased expressions of TNF-α and TNF receptors were found in leukocytes and placenta of women with preeclampsia." (PMID 25302305, 2014). "Cytokines, such as tumor necrosis factor-α (TNF-α) and IL-1, have been shown to be elevated in preeclampsia." (PMID 23690796, 2013). "PEG10 expression is decreased in early onset preeclampsia, with negative regulation in settings of hypoxia and TNF-α inflammation, but it has not been shown to affect cell differentiation or proliferation." (PMID 41141914, 2025). "Women with preeclampsia had significantly higher levels of CRP, IL-4, IL-6, IL-8, IL-10, and TNF-α." (PMID 41346429, 2025). "In addition, the circulating levels of pro-inflammatory cytokines, such as IL-6, TNF-α, and chemokines IL-8, IP-10 (interferon-gamma-induced protein 10) and MCP-1 (monocyte chemoattractant protein 1) are elevated in preeclampsia." (PMID 41346429, 2025). "However, it has been suggested that the pro-inflammatory cytokines TNF-α and IL-1β are involved in IUGR and preeclampsia." (PMID 39065188, 2024). "ANP receptor expression is significantly upregulated in preeclamptic vasculature, but not because of exposure to preeclampsia toxins TNFα or sFlt-1." (PMID 37047162, 2023). "While previous studies used TNF-α alone or in combination with platelets and thrombin, we utilized a MIX of three different cytokines in order to better mimic the cytokine storm that endothelial cells experience during preeclampsia." (PMID 37446111, 2023). "Statins have been reported to attenuate inflammatory markers [e.g., high-sensitivity C-reactive protein (hs-CRP), interferon-γ (IFN-γ), tumor necrosis factor-α (TNF-α)], as well as improve imbalance in the T helper cell type 1 (Th1) over Th2 cytokine responses observed in preeclampsia." (PMID 37255938, 2023). "TNF-α and the insulin-like growth factor-I change NFKBIE DNA methylation in the human placental cell line and also lead to pathological alterations in the placenta, which results in preeclampsia." (PMID 37505866, 2023). "For example, pathological models used for preeclampsia can arise from genetic modifications as the STOX-1 model, from surgical procedures as the reduced uterine perfusion pressure (RUPP) model, or from drug induction with TNF-α." (PMID 35625672, 2022).
preeclampsia (continued). "Another study observed lower, but not statistically significant, serum TNF-α concentrations in women with preeclampsia compared to women with healthy pregnancy at ≥20 weeks." (PMID 33680514, 2021). "Women with preeclampsia also showed increases in pro-inflammatory cytokines IL-6 and IL-8 but not TNF-alpha in the CSF compared to women with normotensive pregnancies." (PMID 34831266, 2021). "For instance, in the plasma of mothers with preeclampsia, concentrations of IL-6, but not TNFα or IL-1β, were higher than those reported in normal patients." (PMID 34696359, 2021). "Taken together, these findings suggest that TNF-α is able to regulate autophagic activity via suppressing NF-κB, which might be the mechanism related to ULBP1 in preeclampsia pathogenesis." (PMID 32626772, 2020). "Furthermore, high concentrations of TNF-alpha, IFN-gamma, and IL-6 have been measured in the amniotic fluid of mothers undergoing spontaneous miscarriage, preterm delivery, and preeclampsia." (PMID 31790466, 2019). "During normal pregnancy, sEng liberation is inhibited from the placenta and endothelium through proinflammatory cytokines such as TNF-α and IFN-γ, but in a preeclamptic pregnancy sEng is increased along with sFlt-1 before the onset of the clinical symptoms of preeclampsia." (PMID 30809262, 2019). "Levels of TNF-α, IL-1β, and IL-6 were increased but IL-10 was decreased in culture medium of monocytes from women with preeclampsia compared with those from nonpregnant and normotensive pregnant women (all p < 0.01)." (PMID 31138166, 2019). "In the present study, we proposed to determine the concentration of eHsp‐60, ‐70, IL‐1β and TNFα in the serum of pregnant patients with 34 weeks of gestation with and without clinical evidences of preeclampsia (PE)." (PMID 30133944, 2018). "In addition, circulating levels of IL6, tumor necrosis factor alpha (TNFα) and monocyte chemoattractant protein 1 (MCP-1) have been found to be elevated in preeclampsia." (PMID 29145462, 2017). "Subsequently, preeclampsia plasma mediators significantly increased enodthelial TLR-9 gene expression (1.43 ± 0.17 fold, n = 8, P < 0.01) and pro-inflammatory TNF-α gene expression (2.65 ± 0.17 fold, n = 8, P < 0.01) in HUVEC respectively, compared to uncomplicated pregnancy." (PMID 27604418, 2016). "To evaluate the in vivo pathophysiological consequences of AT1-AAs to the retina, we introduced AT1-AA purified from severe preeclampsia into pregnant rats on day 13 of gestation to determine the effect of AT1-AA on hypertensive retinopathy and level of TNF-α and VEGF in vitreous humor." (PMID 27381670, 2016). "Plasma TNF-α and VEGF levels in severe preeclampsia group were detected by ELISA." (PMID 27381670, 2016). "The inflammatory cytokines, IL6, TNF α and CRP are elevated in severe preeclampsia and may mediate some of the clinical manifestations of the disorder." (PMID 26113950, 2015). "In preeclampsia, the ischemic placenta may contribute to the maternal endothelial cell dysfunction by enhancing the synthesis of IL6, TNF α and IL8." (PMID 26113950, 2015). "As a result of these controversies, we decided to measure the serum concentrations of IL-6, TNF α, and C reactive protein (CRP) in women with severe preeclampsia, and to determine if they differ from those of gestational age matched, normotensive, pregnant women." (PMID 26113950, 2015). "This study is to determine the concentrations of IL-6, TNF α, and C reactive protein (CRP) in women with severe preeclampsia, and compare with those of gestational age- matched normotensive pregnant women and to correlate CRP levels with markers of organ damage in women with preeclampsia." (PMID 26113950, 2015). "We examined whether morphological differences could be detected by T2 mapping in the placenta of mice subjected to two experimental models of preeclampsia; namely the RUPP model and the inflammatory cytokine imbalance model (TNF-α)." (PMID 23555853, 2013).